TNF (tumor necrosis factor)
Diseases named in the same sentence as TNF in open-access papers (continued):
Sharing a sentence is not in itself a finding about the gene and the disease.
endometriosis (continued). "Notably, the eutopic endometrium of women with endometriosis exhibits elevated levels of inflammatory cytokines, including IL-1β, TNF-α, and IL-8 compared to the control, suggesting that this pro-inflammatory environment contributes to impaired decidualization in endometriosis." (PMID 40072055, 2025). "TNF-α may be one of the essential players in the pathogenesis of endometriosis development." (PMID 38892003, 2024). "Sakamoto Y demonstrated that treatment with gonadotrophin-releasing hormone agonists (GnRHa) could decrease the expression of IL-8 by inhibiting NF-κB signaling induced by TNF-α, which results in the suppression of inflammation and the development of endometriosis." (PMID 36865552, 2023). "Similarly, monocytes from patients with endometriosis produce increased levels of TNF-α." (PMID 37545483, 2023). "TNF-alpha may thus have a significant role in the inflammatory component of endometriosis." (PMID 37936116, 2023). "Cytokines and inflammatory mediators such as IL-1, IL-6, IL-8, IL-12, IFN-γ, MCP-1, TNF-α, sTNFR-1, and CCL5 (RANTES), which are measured in the serum and PF of patients with endometriosis, have the potential to serve as diagnostic biomarkers in patients with endometriosis." (PMID 36865552, 2023). "The interaction between ER-β and the inflammasome machinery increases IL-1β levels and inhibits TNFα-induced apoptosis, resulting in immune escape, the survival of ESCs, and the epithelial-mesenchymal transition pathway, which plays an essential role in the pathogenesis of endometriosis." (PMID 36865552, 2023). "Moreover, elevated levels of TNFα in peritoneal fluid activate NFκB signaling along with other proinflammatory factors, which ultimately promote the proliferative and inflammatory characteristics of endometriosis." (PMID 37205467, 2023). "Thus, DNG may reduce cell viability and proliferation induced by estradiol, TNF-α, IL-1β, and IL-32, and inhibit the endometriosis pathogenesis by decreasing PCNA expression." (PMID 36428561, 2022). "Proinflammatory cytokines such as TNF-α, IL-1β, IL-6, and IFN-γ initiate and amplify inflammatory and immune responses by signaling the recruitment of additional proinflammatory mediators and immune cells to the site of injury and have been implicated in endometriosis development and progression." (PMID 35409294, 2022). "Also, Glisodin® administration significantly reduces TNF-α levels in endometriosis rats." (PMID 36082333, 2022). "Additionally, TNF-α and IL-1β affect nuclear signaling, which may contribute to the pathogenesis of endometriosis." (PMID 36428561, 2022). "Of note, the cytokines inhibited by MiodesinTM, such as IL-8, IL-6, IL-1β, and TNF-α are thought to have a key role in the inflammatory process in endometriosis, becoming an interesting tool as an adjuvant for therapeutic schemes in the treatment of endometriosis." (PMID 35164046, 2022). "As research on SNP TNF-α − 1031 T/C and HCC risk is still limited, we only found five studies investigating this SNP, even though many studies have shown significant association between this SNP with other diseases such as polycystic ovary syndrome and endometriosis." (PMID 33228594, 2020). "Increased levels of TNFα and glycodelin correlate with central hyperexcitability in response to repeated electrical stimulation and altered pain response to nociceptive withdrawal reflex, as well as higher levels of menstrual pain experienced by endometriosis patients." (PMID 33132854, 2020). "In addition, we investigated whether treatment of control ME-SFCs with inflammatory cytokines (TNF and IL-1β) could induce an endometriosis-like phenotype." (PMID 36304708, 2020). "Similarly, cultured stromal cells from endometrial and endometriosis lesions express TNF ex vivo." (PMID 36304708, 2020).
endometriosis (continued). "In addition, GFW could regulate toll-like receptor signaling, TNF signaling, NF-kappa B signaling, neuroactive ligand-receptor interaction, and affect the occurrence and development of endometriosis based on network pharmacology." (PMID 32210799, 2020). "According to our data, inflammatory reactions with an increased TNFα concentration in local peritoneum, such as the endometriosis or bacterial infection related adnexitis, could result in over‐expression of TNFα, and induce follicle atresia, apoptosis, and autophagy." (PMID 26161038, 2015). "Therefore, in order to search a possible mechanism of ultralong GnRHa therapy, we investigated the effect of ultralong GnRHa therapy on intrafollicular concentrations of tumor necrosis factor alpha (TNFα), oxidative stress markers, and antioxidants in patients with endometriosis." (PMID 25331066, 2014). "Experimental studies on human endometriotic cell lines and murine models have demonstrated that the activation of PPARγ by ciglitazone and rosiglitazone may inhibit endometriosis proliferation and that pioglitazone reduces the TNF-alpha-induced IL-8 production and the proliferation of ESCs." (PMID 25165691, 2014). "In particular, according to these latter authors, increased IL10 production may partially contribute to the disturbed immune regulation in patients with endometriosis, because it attenuates TNF-α-induced IL6 synthesis via NF-kappaB and MAPK pathways in endometriotic cells." (PMID 23843796, 2013). "Compared with untreated endometriosis, terazosin significantly reduced SF-1, PGE2, IL-6, IL-8, TNF-α, VEGF and HIF-1α across compartments (all p < 0.001), comparable to leuprolide (p = 1.000)." (PMID 42123670, 2026). "TNF-α, together with IL1-β, was shown to stimulate IL-8 production, contributing to the inflammatory milieu and pain in endometriosis." (PMID 40724945, 2025). "Prostaglandin E2, TNFα, NGF, RANTES, IL-8, and IL-1β are elevated within the peritoneal fluid of endometriosis patients." (PMID 40508002, 2025). "Higher levels of inflammatory mediators such as tumor necrosis factor α (TNFα), interleukins, prostaglandin E2 (PGE2), nerve growth factor (NGF) and chemokine RANTES/CCL5 were found in lesions and perioneal fluid of endometriosis patients." (PMID 40948761, 2025). "Recent studies on immune protein analysis have demonstrated that the expression levels of TNFα, MDC (monocyte chemoattractant protein, also referred to as CCL22), and IL-1α are elevated in patients suffering from endometriosis-related chronic pain." (PMID 40004233, 2025). "It has been demonstrated that some cytokines, such as tumor necrosis factor-alpha (TNF-a), interleukin-6 (IL-6), and IL-8, are different in endometriosis-affected women compared to controls." (PMID 38555302, 2024). "Many inflammatory factors, such as tumor necrosis factor (TNF)-alpha, interleukin (IL)-1beta, IL-33 and IL-6, were upregulated in peritoneal fluid of women with endometriosis." (PMID 38961373, 2024). "Dysregulation of proinflammatory cytokines (TNF-alpha, IL6...) or IL24 has been demonstrated to play an important role in the pathophysiology of eutopic and ectopic endometriosis." (PMID 38396681, 2024). "In this study, both the TNF-α positive area and mRNA levels of TNF-α were elevated in the endometriosis group compared with those in the control group." (PMID 38612685, 2024). "MiR-196a may contribute to progesterone resistance in endometriosis and miR-144-3p has been shown to correlate with cell survival status in human endometriotic lesions and is involved in the regulation of inflammatory mediators such as IL-6, IL-1β, TNFα, PTGS2 and COX2." (PMID 39457531, 2024). "SASP gene products identified by RNAseq include many inflammatory biomarkers that have been historically analyzed in endometriosis, including IL-1β, IL-6, IL-8, CCL5, TNF-α, CCL2, MMP3, HMGB1, p16, and p21." (PMID 38879630, 2024).
endometriosis (continued). "Elevated levels of pro-inflammatory cytokines, such as interleukin-6 (IL-6), interleukin-1beta (IL-1β), tumor necrosis factor-alpha (TNF-α), and prostaglandin E2 (PGE2) have been consistently identified in women diagnosed with endometriosis." (PMID 39257907, 2024). "Peritoneal mesothelial cells of women with endometriosis produce MCP-1 in response to IL-1α and TNF-α stimulation." (PMID 38928175, 2024). "Specifically, the levels of TNFα, IL1β, and IL6 are increased in pelvic MΦ isolated from endometriosis patients." (PMID 38559689, 2024). "In response to multiple factors such as IL-1β, TNF-α, and TLR4, endometriotic cells activate the NF-κB signaling pathway, affecting endometriosis initiation and progression." (PMID 36769226, 2023). "Using RT-QPCR, the expression of several miRNAs were quantified in primary cells derived from eutopic endometrium of endometriosis subjects (EESC) and normal endometrial stromal cells (NESC) and also TNFα treated NESCs." (PMID 37205467, 2023). "There are other components of innate immunity, including TNF-α, IL-1β, IL-6, IL-17A, ICAM-1/LFA-1, and HMGB-1, that participate in the pathogenesis of endometriosis." (PMID 36865552, 2023). "Using RT-qPCR, the expression of several miRNAs was quantified in primary cells derived from eutopic endometrium of endometriosis subjects (EESC) and normal endometrial stromal cells (NESC), and also TNFα-treated NESCs." (PMID 37389684, 2023). "The TNF and IL6 data require a more thorough analysis but, in general, support the histological observation of glial activation during endometriosis." (PMID 36879305, 2023). "Inflammatory mediators, such as tumor necrosis factor-α (TNF-α) and interleukin-1β, can increase human endometrial haptoglobin production in female individuals with endometriosis." (PMID 36765791, 2023). "Activation of macrophages via the NF-κB signaling pathway leads to the release of interleukins, TNFα, COX-2, and VEGF, which further promotes inflammation in endometriosis." (PMID 37834449, 2023). "The inflammatory mediators in endometriosis include prostaglandins, interleukins (IL), vascular endothelial growth factor (VEGF), tumor necrosis factor (TNF-α), and nerve growth factor (NGF)." (PMID 36983810, 2023). "These bioactive compounds reduce the expression of IL-6, IL-8, TNF-α, and COX-2, presenting a reduction of VEGF expression and matrix metalloproteinase-9 activity, thus inhibiting the development of endometriosis." (PMID 37108664, 2023). "The expression of IL-6, TNFα, and IL-1β, as markers of inflammation, and TGFβ, as a marker of fibrosis, could be useful tools to predict the response of an individual’s immune system to the different progestins suitable for the treatment of menopausal inflammatory disorders, including endometriosis." (PMID 37298830, 2023). "The levels of TNF-α, IL-1, IL-6, IL-1β, and transforming growth factor β (TGF-β) in the TLR cascade are known to be altered in endometriosis patients." (PMID 37033937, 2023). "With regards to the HBOT effect on the inflammatory mediators in endometriosis, it has been reported that HBOT showed an observable effect on lowering the TNF-α levels after 6 wk of treatment." (PMID 35911854, 2022). "The transcriptional activity of a number of proinflammatory cytokines/chemokines, such as IL-1, IL-6, IL-8, TNF-α, RANTES, MIF and ICAM1, is activated by NFκB signaling, demonstrating the key role of NFκB in the inflammatory response in endometriosis." (PMID 36359004, 2022). "Further, increased levels of TNF-α, IL-1β, IL-6, and IFN-γ have been detected in the serum, peritoneal fluid, and endometrium of women with endometriosis." (PMID 35409294, 2022). "In rat models with surgically-induced endometriosis, V. opulus significantly decreased the volume of endometriotic lesions, and lowered the serum levels of IL-6, VEGF and TNF-α." (PMID 33804660, 2021).
endometriosis (continued). "All four FB subclusters were involved in MAPK, TNF, IL-17, and TGF-β signalling pathways, which supported the disease state, and were relevant to the development of endometriosis." (PMID 34233737, 2021). "For example, a decreased PR-B/PR-A ratio was demonstrated in endometrial cells after pretreatment with either tumor necrosis factor-alpha (TNF-α) and in peritoneal fluid obtained from women with advanced-stage endometriosis." (PMID 33411206, 2021). "This study aimed to determine the effects of bone marrow mesenchymal stem cell transplantation on tumor necrosis factor-alpha (TNF-α) receptor 1 (TNFR1) expression, granulosa cell apoptosis, and folliculogenesis in endometriosis mouse models." (PMID 34475699, 2021). "This study was conducted to determine the effects of bone marrow mesenchymal stem cell transplantation on tumor necrosis factor-alpha (TNF-α) receptor 1 (TNFR1) expression, granulosa cell apoptosis, and folliculogenesis in endometriosis mouse models." (PMID 34475699, 2021). "The peritoneal fluid of endometriosis is characterized by the enhanced concentration of inflammatory mediators like IL-1, IL-6, IL-8, TGF-β, TNF-α, VEGF, cyclooxygenase-2 (COX-2), and monocyte chemoattractant protein 1 (MCP-1)." (PMID 33919512, 2021). "Hitherto, TNF-α, PGE2, and MIF (human macrophage migration inhibitory factor) have been proposed for the suppression of inflammation in endometriosis." (PMID 33435569, 2021). "GNRH1, PGR, TNF, CYP19A1, and IL6 were mentioned with the highest frequencies in endometriosis-related articles." (PMID 34917684, 2021). "Aromatase inhibitors, GnRH antagonists, anti-tumor necrosis factor- α (TNF-α), antiangiogenic factors and selective progesterone receptor modulators are the newest medical therapies for endometriosis." (PMID 33804660, 2021). "In endometriosis, C. rotundus decreased inflammation by mainly targeting the following pathways: HIF-1 signaling pathway, TNF and MAPK signaling pathway." (PMID 33804660, 2021). "The levels of numerous cytokines, including interleukin-1β (IL-1β), IL-6, IL-8, TNF-α, and transforming growth factor-β (TGF-β), are higher in the peritoneal fluid of women with endometriosis than those in that of healthy control." (PMID 34616540, 2021). "In endometriosis, the inflammatory mediators secreted include prostaglandins, vascular endothelial growth factor (VEGF), tumor necrosis factor (TNF-α), nerve growth factor (NGF), and interleukins (IL)." (PMID 33435569, 2021). "Indeed, endometriosis is considered a pelvic inflammatory condition; in women with endometriosis, peritoneal fluid is characterized by an increased number of activated macrophages and high levels of pro-inflammatory cytokine/chemokine, such as tumor necrosis factor-α (TNFα) and interleukin-8." (PMID 32325785, 2020). "Neutrophils in the peritoneal fluid of endometriosis increase the production of VEGF in the presence of IL-6, TNF-α, LPS, and estrogen." (PMID 32334621, 2020). "Previous studies have also found that EMT can be induced by pro-inflammatory cytokines in endometriosis, such as TGF-β38, tumor necrosis factor (TNF)-α39 and interleukin (IL)-640." (PMID 32439908, 2020). "In the baboon model, treatment with anti-TNF antibodies and soluble TNFR1 significantly reduced the induction and progression of endometriosis." (PMID 36304708, 2020). "Treatment was also associated with a decline in mRNA expression of several pro‐inflammatory cytokines including IL‐6, TNF‐α, IL‐1β and TGF‐β, known to be highly expressed in endometriosis." (PMID 31904910, 2020). "The researcher’s common point of view is that in endometriosis, NF-kappa B activated macrophages release IL-1, 6, 8, COX-2, TNF-alpha, and vascular endothelial growth factor (VEGF); thus, perpetuating the inflammatory pathway." (PMID 32143439, 2020).
endometriosis (continued). "In the current study’s in vivo experiment, the levels of TNF-α, IL-1β of serum and VEGF of endometriosis lesions significantly decreased in the FC groups at doses of 10, 50, and 150 mg/kg compared with the E2 group." (PMID 33266505, 2020). "In this study, the proportion of rats with the high level of TNF-α and COX-2 was increased in the surgically-induced endometriosis rats compared to the sham-operated rats." (PMID 32685413, 2020). "In the last decades, immunological molecules and inflammatory cytokines have been extensively studied for their potential as noninvasive biomarkers for endometriosis, with the most representative being IL-1, IL-6, IL-8, interferon-γ (IFN-γ), MCP-1, and TNF-α." (PMID 32143439, 2020). "Concentrations of tumor necrosis factor-α (TNF-α) are higher in PF and serum of endometriosis patients, especially in early stages of the disease." (PMID 32145751, 2020). "The research found the three proinflammatory cytokines interleukin (IL)‐1, IL‐6 and tumor necrosis factor (TNF)‐alpha, are all involved in the development of endometriosis." (PMID 30828987, 2019). "Increased inflammatory activity is also present in endometriosis, through the overproduction of Interleukin (IL)-1, IL-6, IL-8, monocyte chemo-attractant protein-1, RANTES, tumor necrosis factor (TNF)-α and TNF-β." (PMID 30008440, 2018). "The semi-quantitative results of TNFα expression in bovine COC cultured in control, endometriosis, and endometriosis+curcumin groups were 0.00 ± 0.00; 8.67 ± 3.72; and 2.17 ± 1.69, respectively." (PMID 31417983, 2018). "Both EtOAc and methanol(MeOH)extracts of V. opulus L. showed significant inhibition of TNF-α, VEGF, and IL-6 levels in a rat model of surgically induced endometriosis." (PMID 30402122, 2018). "John's wort oils (HrHp oil) significantly decreased the volumes of endometriotic implants and reduced the levels of TNF-α, vascular VEGF and IL-6 in peritoneal fluids in a surgically induced endometriosis rat model." (PMID 30402122, 2018). "Extracts of S. miltiorrhiza have also shown promise in treating endometriosis by markedly reducing the serum levels of CA125 and the levels of IL-18 and TNF-α, by significantly increasing the levels of IL-13 in the peritoneal fluid in a rat model." (PMID 30402122, 2018). "IL-6 and TNF-α, activate intracellular signal molecules to induce production of O2•- and H2O2 during the pathogenesis of endometriosis via the respiratory burst NADPH oxidase system." (PMID 30555421, 2018). "Indeed, the percentage of PF macrophages with the Fas receptor in patients at stage III/IV of endometriosis was more than twofold higher than that in stage I. This situation could be the result of a higher concentration of TNFα in the peritoneal fluid of women with endometriosis." (PMID 29226157, 2017). "Arici and colleagues reported that mesothelial cells isolated from the PF of women with endometriosis not only produce MCP-1 in response to IL-1α and TNF-α stimulation, but also constitutively produce the cytokine as well." (PMID 26247027, 2015). "Peritoneal macrophages are known to express inflammatory cytokines, such as IL-6, IL-1β and tumor necrosis factor alpha (TNF-α) and to be increased in number and more activated in patients with endometriosis." (PMID 24039864, 2013). "Underlining the inflammatory nature of the condition is the fact that TNFα, ENA-78, and IL-6 are also elevated in the serum of women with endometriosis." (PMID 24453419, 2013). "Several cytokines including interleukin (IL)-1, 6, 8, 10, tumor necrosis factor (TNF)-α, and vascular endothelial growth factor (VEGF) were reported to be increased in the peritoneal fluid (PF) of women with endometriosis." (PMID 19735579, 2009). "A positive correlation between concentrations of tumor necrosis factor (TNF)-α in the peritoneal fluid and endometriosis has been reported." (PMID 16018814, 2005).